CD4 (CD4 molecule)
Diseases named in the same sentence as CD4 in open-access papers (continued):
Sharing a sentence is not in itself a finding about the gene and the disease.
tropical spastic paraparesis (80 papers, 2005 to 2026). "Approximately 5% of infected individuals develop an aggressive malignancy of CD4+ T-cells known as adult T-cell leukemia/lymphoma (ATL) or HTLV-1-associated myelopathy/tropical spastic paraparesis (HAM/TSP) after a prolonged period of clinical latency." (PMID 34019588, 2021). "HTLV-1 is the etiological agent of two major diseases: adult T-cell leukemia (ATL), a disease characterized by malignant proliferation of CD4+ T-lymphocytes, and tropical spastic paraparesis/HTLV-1-associated myelopathy (TSP/HAM), a neurodegenerative condition." (PMID 21994758, 2011). "HTLV-1 infection is associated with adult T cell leukemia/lymphoma (ATLL), mature CD4+ T cell neoplasms, and HTLV-1-associated myelopathy/tropical spastic paraparesis (HAM/TSP), a chronic and progressive neurodegenerative disease." (PMID 33632146, 2021). "A small percentage of HTLV-1-infected individuals develop adult T-cell leukemia (ATL), a CD4+ lymphocyte malignancy, and various lymphocyte-mediated inflammatory diseases such as HTLV-1 associated myelopathy/tropical spastic paraparesis (HAM/TSP)." (PMID 18474092, 2008). "HTLV-1+ patients suffering from tropical spastic paraparesis have decreased frequencies of Foxp3+CD4+CD25+ Treg as well as impaired Treg functions." (PMID 16800882, 2006). "Following permanent host cell genome integration, predominantly in CD4 + T-lymphocytes, HTLV-1 most frequently causes adult T-cell leukaemia/lymphoma (ATL) or HTLV-1-associated myelopathy (HAM), formerly tropical spastic paraparesis." (PMID 35908019, 2022). "However, approximately 5–10% of HTLV-1 carriers develop serious diseases, such as adult T cell leukemia/lymphoma (ATL), an aggressive malignancy of CD4+ T cells, and HTLV-1-associated myelopathy/tropical spastic paraparesis (HAM/TSP), a debilitating neuroinflammatory condition." (PMID 40431738, 2025). "Viral infection can also cause HTLV-1-associated myelopathy/tropical spastic paraparesis (HAM/TSP), a neurological disorder characterized by a chronic inflammatory response against HTLV-1-infected CD4+ T-cell infiltrates in the central nervous system." (PMID 35062342, 2022). "Diseases resulting from HTLV-1 infection include an aggressive CD4+ T-cell malignancy called adult T-cell leukemia/lymphoma (ATL) and a debilitating, progressive neurologic disorder called HTLV-1-associated myelopathy/tropical spastic paraparesis (HAM/TSP)." (PMID 37685922, 2023). "HTLV-1 infection can lead to the development of an aggressive CD4+ T-cell malignancy, adult T-cell leukemia/lymphoma (ATL), or a neurological disorder called HTLV-1-associated myelopathy/tropical spastic paraparesis (HAM/TSP)." (PMID 35958554, 2022). "The virus is associated with an aggressive CD4+ adult T-cell lymphoma/leukaemia (ATLL) and inflammatory diseases such as HTLV I uveitis (HU), infective dermatitis, arthropathy, and HTLV-1-associated myelopathy/tropical spastic paraparesis (HAM/TSP)." (PMID 33562822, 2021). "Besides the aggressive malignancy of CD4+ T cells, HTLV-1 infection induces in 3–7% of subjects chronic inflammation processes including a serious and progressive neurological disease designated HTLV-1-associated myelopathy/tropic spastic paraparesis (HAM/TSP) as well as uveitis and dermatitis." (PMID 31783769, 2019). "HTLV-1 is the etiological agent of two main very severe diseases: a lympho-proliferative disorder, of mainly CD4 T-cells, named adult T-cell leukemia/lymphoma (ATL), and a chronic neuromyelopathy named tropical spastic paraparesis/HTLV-1 associated myelopathy (TSP/HAM)." (PMID 31842895, 2019). "HTLV-1 is another member of the Retroviridae family and the etiological agent of the aggressive CD4+ T cell proliferative malignancy, adult T-cell leukemia (ATL), as well as a progressive neurological disease known as HTLV-1-Associated Myelopathy/Tropical Spastic Paraparesis (HAM/TSP)." (PMID 26751489, 2016).
tropical spastic paraparesis (continued). "These patients are more prone to develop neurological complications, particularly HTLV-1 associated myelopathy/ tropical spastic paraparesis (HAM/TSP) and may progress faster to AIDS with higher levels of activation markers, despite their higher CD4 T cell counts." (PMID 26329520, 2015). "These Treg-like ATL cells do not produce IFN-γ contrary to the HTLV-I infected CD4+CD25+ cells in the neuro-inflammatory HTLV-I Associated Myelopathy/Tropical Spastic Paraparesis (HAM/TSP), which display a non-Treg phenotype with decreased expression of Foxp3 and increased levels of IFN- γ." (PMID 23962110, 2013). "Similarly to HIV, the enveloped positive single-stranded RNA virus HTLV-1 infects CD4+ T lymphocytes, and it is the causative agents of two diseases: acute T-cell leukaemia/lymphoma (ATLL) and a demyelinating disease known as HTLV-1-associated myelopathy/tropical spastic paraparesis (HAM/TSP)." (PMID 32708331, 2020).
fibrosis (79 papers, 2010 to 2026). the formation of excess fibrous connective tissue in an organ or tissue in a reparative or reactive process. "The following factors were independently associated with fibrosis (odds ratio (OR) and CI): (i) older age (per 10 years; OR = 1.80 (95% CI, 1.27 to 2.55), p = 0.001) and low CD4+ T‐lymphocyte count (<200 cells/mm3; OR = 7.80 (95% CI 2.09 to 29.09), p = 0.002)." (PMID 30394678, 2018). "Fibrosis regression was significantly associated with higher CD4+ cell counts (P = 0.009) and lower fasting triglyceride levels (P = 0.007) at TDF-initiation." (PMID 28362068, 2017). "For example, the 5-year risk of LRD in patients with ≥F2 fibrosis (versus <F2) increased from 27-fold to 50-fold in patients with a CD4 cell count ≥200 cells/microliter and <200 cells/microliter, respectively." (PMID 25253564, 2014). "While TMNP show compelling efficacy in acute inflammation, key questions require resolution: First, whether CD4+CD8a+ T cell expansion predispose to post-VILI fibrosis merits investigation using lineage-tracing models." (PMID 40709179, 2025). "Finally, single-cell T cell receptor (TCR) analysis demonstrated that SG CD4+ T cell clonal expansions are antigen-driven and are associated with reduced salivary flow and increased SG fibrosis." (PMID 32650575, 2020). "Previous AIDS-defining illness was associated with transitions to fibrosis progression in univariable analysis and lower nadir CD4 cell count in patients with baseline F0–F1–F2 fibrosis were associated with progression to F3–F4 fibrosis by the end of follow-up." (PMID 28362068, 2017). "As SS patients are usually diagnosed in the fourth decade or later, and loss of salivary flow and SG fibrosis correlate with patient age, we next asked whether age could explain any associations observed between the proportion of SG CD4+CD45RA− T cells and features of SS." (PMID 32650575, 2020). "Each of the onset of respiratory distress (survival time) and fibrosis score was significantly negatively correlated with %CD4 + lymphocytes and with the CD4+/CD8 + ratio in the lung." (PMID 41261392, 2025). "Notable variations in CD4+ T cell states and compositions were observed between Fibrosis+ and Fibrosis− LMs." (PMID 41258075, 2025). "The analysis using Ro/e and MiloR algorithms revealed a higher proportion of CTLA4_CD4_Treg, CXCL13_CD4_Tex and STMN1_CD4_Tpro cells in the Fibrosis+ LM, whereas ANXA1_CD4_Tm and FOS_CD4_Tm cells were more prevalent in the Fibrosis− LM." (PMID 41258075, 2025). "While the focus of this work is fibrosis, the reduced CD4+CD8+ DP cells and the CD4+ Treg enrichment in Jag1Ndr/Ndr mice is intriguing given the prominent roles of Notch in immune cell development." (PMID 39358604, 2024). "Fibrosis progression was associated with higher HMGB1 and lower percentage nadir CD4+ T-cell count, highlighting the importance of early initiation of HBV-active ART." (PMID 38518655, 2024). "Briefly, at 12MPT, those with advanced fibrosis presented lower counts of CD4 cells than those with mild fibrosis, which is also reflected in a lower CD4/CD8 ratio." (PMID 38107019, 2023). "Nevertheless, a profibrosis effect of CD4+CD25hiFoxp3+ Tregs has been shown in bleomycin-induced PF and other types of fibrosis animals, so the potential role of Tregs in PF remains uncertain and can be controversial." (PMID 37731513, 2023). "IL-17 gene knockout mice with AE-IPF had quicker body weight recovery, milder pulmonary inflammation and fibrosis, stronger IL-22+CD4+T, TGF-β+ γδ T and Treg cell responses, and weaker neutrophil and eosinophil responses than wild-type mice with AE-IPF." (PMID 35836804, 2022). "In this study, the group with fibrosis showed a higher frequency of CD4+ T lymphocytes expressing IL-13 when compared to individuals without fibrosis, as well as higher levels of this cytokine in the supernatant of PBMCs cultures stimulated with SEA." (PMID 33692784, 2021).
fibrosis (continued). "We did not observe a significant difference in correlation of the frequency of CD4+T cells expressing TGF-β with CD4+ IL-4+ and CD4+IL-13+ T cells in the group of individuals with periportal fibrosis." (PMID 33692784, 2021). "After reconstitution of RAG−/− mice with CD4+ T cells or CD8+ T cells in an obstructed kidney model, the reconstitution with CD4+ T cells restores fibrosis, but reconstitution of RAG−/− mice with CD8+ T cells does not significantly influence renal fibrosis." (PMID 34356613, 2021). "We observed a higher frequency of CD4+TGF-β+ T lymphocytes in the cultures of individuals with any grade of periportal fibrosis, both in the PPF/PF and APF/PH groups, compared to the group without fibrosis (p<0.01)." (PMID 33692784, 2021). "To investigate the cellular dynamics of CD4+ T cells during liver inflammation, we induced chronic liver injury and fibrosis in an established procedure by injecting CCl4 for 6 weeks." (PMID 33178216, 2020). "Fibrosis in IgG4-RD is considered to be caused by transforming growth factor-β (TGF-β) secreted by Tregs and CD4 + cytotoxic T cells (CD4 + CTLs)." (PMID 33121169, 2020). "Our results highlight CD4+ memory T cell subsets as important drivers of NAFLD progression from steatosis to fibrosis and provides a humanized mouse model for pre-clinical evaluation of potential therapeutics." (PMID 33013934, 2020). "In a previous study, we described that HIV/HCV‐coinfected individuals with advanced fibrosis presented lower percentages of CD4+ T‐cells and NK cells compared with subjects with minimal fibrosis." (PMID 31536177, 2019). "In this new group of HIV/HCV‐coinfected individuals, we confirmed our previous observations 20 showing that advanced fibrosis subjects displayed the lowest CD4+ T‐cell and NK cell frequencies." (PMID 31536177, 2019). "The number of liver infiltrating CD8+ cells was higher in patients with fibrosis in comparison to F0 patients, and accordantly the CD4/CD8 ratio was lower." (PMID 31318916, 2019). "The level of CD4+ T-cells was similar in nAMD patients with fibrosis and age-matched healthy controls." (PMID 26572732, 2015). "Moreover, IL-3 production by memory CD4+ T cells was essential for aggravation of fibrosis in memory situations." (PMID 41837289, 2026). "Given the predominance of path 1 cells in the Fibrosis+ LM, CD4+ T cells in the TME may trend toward exhaustion or suppression, potentially impacting immunotherapy responsiveness." (PMID 41258075, 2025). "Fibrosis progression was associated with elevated HMGB1 and lower nadir CD4+ T-cell count." (PMID 38518655, 2024). "Moreover, flow cytometry revealed increased expression levels of CD69 and CXCR6 in pulmonary CD4 T cells during fibrosis progression." (PMID 38789926, 2024). "Furthermore, renal inflammatory cell infiltration (F4/80+ and CD4+) and tubulointerstitial fibrosis (Sirius red and fibronectin staining) were ameliorated in SH045-treated NZO mice." (PMID 35743312, 2022). "In contrast, specific ablation of CD4+ T-cells by GK1.5 resulted in mitigated cardiac fibrosis and increased cardiomyocyte proliferation, suggesting that they could negatively regulate heart regeneration in the P8 mice." (PMID 32724455, 2020). "Fibrosis is also mediated by an inflammatory immune response involving CD4+ and CD8+ lymphocytes." (PMID 32551360, 2020). "Depletion of CD4+ T-cells via the lytic anti-CD4 antibody after CI to the P8 heart reactivated juvenile heart regeneration manifested by significantly reduced cardiac fibrosis and increased number of proliferating cardiomyocytes when compared to that of the control group." (PMID 32724455, 2020). "In BIPF we observed a significant reduction of CD4+ Th-cells in the BALF as well as a trend for reduced CD4+ Th-cell numbers in the lung (similar numbers were observed for CD8+ T-cells) early on in the BLM induced fibrosis." (PMID 26971883, 2016).
fibrosis (continued). "B. pseudocatenulatum CECT 7765 also tended to reduce B cells and the CD8+/CD4+ ratio, whose increase is associated with serious liver alterations (e.g. fibrosis), but these latter changes were not statistically significant." (PMID 26161548, 2015). "Furthermore, the intra-hepatic lymphocyte content revealed a significant augmentation of liver CD8 content (P<0.0001), a reduction in CD4 (P<0.0001) and NK (P=0.04) levels in vehicle-treated CCl4 fibrosis-induced animals." (PMID 24340043, 2013). "Our IHC finding of collagen and CD4+ co-localization is in line with previous work revealing that the disruption of lymphoid tissue architecture is linked to CD4+ T-cell loss in all stages of HIV infection, as it suggests that gut fibrosis may be a contributing mechanism of CD4+ T-cell depletion." (PMID 38016163, 2024). "Studies have demonstrated that T cell levels (e.g., CD4+ T and CD8+ T cells) in lung tissue are significantly correlated with fibrosis severity." (PMID 40115251, 2025). "B cells, CD4 T cells, CD8 T cells, and dendritic cells were activated in advanced fibrosis, accompanied by increased infiltration of γδ T cells, MDSCs, and natural killer T cells (NKTs), and most of these are established pro-fibrosis immunocytes." (PMID 39257588, 2024). "Percentage of T-helper cells (CD4+CD8−) and cytotoxic T cells (CD4−CD8+) in fibrosis group were significantly lower than the naive group." (PMID 35307625, 2022). "The splenic CD4+ T cells, CD8+ T cells, macrophages, monocytes, and neutrophils subpopulations were decreased in the HOCl induced fibrosis mouse, whereas the percentage of CD19+ B cells was increased." (PMID 31481954, 2019). "We quantified FOXP3+, CD4+, CD8+ and CD20+ cells in liver biopsies of 35 male subjects matched by age and ISHAK fibrosis score, 12 HIV monoinfected, 11 HCV monoinfected and 12 HIV/HCV coinfected." (PMID 24597693, 2014). "Exposure variables included age, sex, CD4+ cell count, HCV genotype, HCV and HIV viral loads, liver histology (METAVIR fibrosis scoring system) and previous treatment." (PMID 23874441, 2013). "Both CD4+CD45RO+ and CD8+CD45RO+ T-cell telomere length were significantly shorter in HCV-infected subjects with severe fibrosis compared to controls and subjects with mild fibrosis." (PMID 20462651, 2010). "Therefore, we compared the migration of Th (CD4+ T), CD3+ T, and CD8+ cytotoxic T cells into the liver in the CCl4-induced fibrosis model." (PMID 40017805, 2025). "CD4+ and CD8+ T cells, the predominant T cell subsets detected in both serum and skin biopsies during the inflammatory response and fibrosis stage of SSc patients, play a crucial role in activating angiogenesis, promoting collagen production, and inducing fibrosis." (PMID 40046046, 2025). "CD4 + lymphocyte % of C3H/HeJ mice exceeded that of C57BL/6J mice at both radiation-induced respiratory distress and in unirradiated controls (P < 0.04) and pulmonary CD4+% was reduced, at distress relative to control levels, in fibrosis responding strains." (PMID 41261392, 2025). "We observed a higher frequency of CD4+IL-10+ T cells in the PPF/PF group compared to individuals without fibrosis." (PMID 33692784, 2021). "We first evaluated the frequency of T CD4+ lymphocytes expressing IL-4, IL-5, and IL-13 after stimulation with SEA, since these cytokines are the main molecules involved in the pathogenesis of periportal fibrosis related to Schistosoma mansoni infection." (PMID 33692784, 2021). "Proportions of SG CD4+ but not CD8+ T cells associated with increasing focus score, corneal damage, and serum antibody levels, while the overall numbers of memory T cells correlated with SG fibrosis." (PMID 32650575, 2020). "Strong induction of Ova-specific CD4 and CD8 INF-ɣ responses were detected in all LmAIO-vaccinated groups and they were independent of fibrosis, demonstrating comparable INF-ɣ responses between NaCl, oil, and CCl4 groups." (PMID 35173308, 2022).
fibrosis (continued). "We observed an increase in the frequency of CD4+ T cells expressing these cytokines in the group of individuals with periportal fibrosis (PPF/PF), compared to individuals without fibrosis (WF/IFNE)." (PMID 33692784, 2021). "Taken together, our results show that multicytokine-producing CD4+ T cells, mainly characterized by the expression of IL-17A, are particularly enriched in the liver of those NASH patients with fibrosis compared with those without fibrosis." (PMID 36625344, 2023). "Among the different multicytokine-producing CD4+ T cells, we discovered that CD4+ T cells producing mainly IL-17A, but not exclusively — i.e., CD4+ T cells with a Th17 polarization state — were significantly enriched in the liver of NASH patients with fibrosis compared with no fibrosis." (PMID 36625344, 2023).